YAP1 (Yes1 associated transcriptional regulator)
Diseases named in the same sentence as YAP1 in open-access papers (continued):
Sharing a sentence is not in itself a finding about the gene and the disease.
gastric cancer (continued). "Notably, the secretion of Interleukin 3 (IL-3) in Yes-associated protein 1 (YAP1) overexpressing and 5-FU-resistant gastric cancer cells induces tumor-associated macrophages to undergo M2-type polarization, promoting their GLUT3 expression and activating glycolysis." (PMID 40264038, 2025). "In the current study, we sought to establish whether Yap1 activity was intrinsically associated with that of gp130/Stat3 signalling-dependent carcinogenesis and to clarify the underlying mechanisms that control gastric cancer initiation and development." (PMID 37957015, 2024). "Research has shown that YAP1 plays a significant role in the onset and progression of tumors, with high expression of YAP1 closely associated with the occurrence and progression of various cancers, including esophageal cancer, pancreatic cancer, lung cancer, thyroid cancer, and gastric cancer." (PMID 38227081, 2024). "In particular, ivermectin suppressed MKN1 gastric cancer cell growth in vitro and in vivo (when used at 10 μM and 10 mg/kg respectively) through the inhibition of the nuclear expression of yes-associated protein 1 (YAP1), which plays a key role in gastric carcinogenesis." (PMID 32668817, 2020). "For example, in lung adenocarcinoma, Piezo1-Ca2+ signalling initiates the tumour-suppressive ROS/Wnt/β-catenin pathway, whereas in gastric cancer, the same signal cooperates with the YAP1/CTGF pathway to drive pro-fibrotic and inflammatory factor expression." (PMID 41437911, 2026). "have demonstrated that miR-205 overexpression specifically targets and downregulates YAP1 expression in gastric cancer cell lines SGC-7901 and HGC-27." (PMID 41001034, 2025). "YAP1 is usually considered as a carcinogen in tumors, which can promote the development of many cancers, including gastric cancer." (PMID 41001034, 2025). "It is reported that METTL3 enhances the proliferation and migration of gastric cancer cells by modifying YAP1 through N6-methyladenosine (m6A)." (PMID 40822927, 2025). "Here, we unveil a previously unrecognized NAT10/XIST/YAP1/VEGFA signaling axis driving vascular abnormalization in gastric cancer (GC) and demonstrate its therapeutic potential in remodeling the tumor immune microenvironment." (PMID 40860183, 2025). "Through its actions, OTUD7B promotes the progression of gastric cancer by enhancing the activity of the YAP1/NUAK2 axis." (PMID 39936032, 2025). "It is reported that m6A-mediated YAP1 boosted migration in gastric cancer and tumorigenesis in chordoma." (PMID 40822927, 2025). "It promotes YAP1 transcription by binding to c-MYC in the YAP1 promoter in gastric cancer and T-cells." (PMID 40649881, 2025). "On the contrary, after knocking out expression of METTL3, the activity of the YAP1 signaling pathway and the proliferation and metastasis of gastric cancer were inhibited by modifying the m6A RNA modification level of the YAP1 gene." (PMID 39009956, 2024). "For example, lncRNA SUNO1 promotes cell cycle progression by controlling the YAP1/Hippo signaling pathway; miR-218 suppresses gastric cancer cell cycle progression via the CDK6/Cyclin D1/E2F1 axis." (PMID 37538116, 2023). "YAP1 is highly expressed in gastric cancer tissues, and promotes the growth, invasion, and drug resistance of tumor cells." (PMID 37894282, 2023). "As a result, OTUB1 promotes gastric cancer cell proliferation, migration, and invasion as well as stemness through YAP1." (PMID 38264570, 2023). "Specifically, AMOTL1 promotes tumorigenesis via interacting with YAP1, a vital factor of the Hippo pathway, to induce its nuclear accumulation in gastric cancer and glioma." (PMID 37558679, 2023). "Studies have shown that SMAD1 is highly expressed in cisplatin-resistant gastric cancer cells and that SMAD1 interacts with YAP1, leading to the increased resistance of gastric cancer cells to cisplatin." (PMID 37685308, 2023).
gastric cancer (continued). "In conclusion, linc01133, a JUN and FOS regulated lncRNA, promoted gastric cancer cell growth as a ceRNA for miR-145-5p via YES1 mediated YAP1 nuclear translocation." (PMID 35017464, 2022). "By binding to C-Myc at the YAP1 promoter, the lncRNA RP11-323N12.5 promotes YAP1 expression in gastric cancer." (PMID 35701841, 2022). "In support of these observations, Striatin 3 has been found to be overexpressed in human gastric cancers, leading to inactivation of the Hippo pathway and hyperactivation of the proto-oncogene YAP1." (PMID 36328247, 2022). "The median DFS was shorter in patients with high YAP1 expression in esophageal and gastric cancer, consistent with our results." (PMID 35911146, 2022). "CLDN6 enhances gastric cancer cell proliferation and invasiveness via the YAP1 and YAP1-Snail1 axis." (PMID 35281827, 2022). "The survival analysis showed that the relationship between YAP1 expression and overall survival in pancreatic and gastric cancer is consistent with our meta-analysis results (–7)." (PMID 35911146, 2022). "This article proved that m6A methyltransferase METTL3 promoted the proliferation and migration of gastric cancer cells through the m6A modification of YAP1." (PMID 34394353, 2021). "MicroRNA-9 and microRNA-137 regulate the hippo-YAP1 axis, giving rise to the development of gastric cancer." (PMID 34082774, 2021). "As a downstream effector of the dysregulated Hippo pathway, activation or overexpression of YAP1 contributed to tumor progression in diverse solid tumors including lung cancer, bladder cancer, ovarian cancer, and gastric cancer." (PMID 33970925, 2021). "Some scholars collected 156 gastric cancer samples and found that 48.7% (76/156) of patients with gastric cancer showed a low expression level of YAP1, while 51.3% (80/156) of the patients with gastric cancer showed a high expression level of YAP1." (PMID 34394353, 2021). "In other words, the poor clinical outcome of gastric cancer patients is correlated with high levels of YAP1 or SOX9." (PMID 34768751, 2021). "Studies have shown that YAP1 knockdown in gastric cancer inhibits cell proliferation and reduces cell invasion and migration." (PMID 34692659, 2021). "The linear regression analysis showed that the YAP1 level positively correlated with the METTL3 level in human gastric cancer tissues." (PMID 34394353, 2021). "In conclusion, this study showed that m6A methyltransferase METTL3 promoted the proliferation and metastasis of gastric cancer through the m6A modification of the YAP1 pathway." (PMID 34394353, 2021). "Yes-associated protein 1 (YAP1) and TAZ, two key factors in the Hippo pathway, exerted oncogenic function via cross-talking with Notch, TGF-β, Wnt/β-catenin in gastric cancer." (PMID 33531900, 2021). "This study showed that m6A methyltransferase METTL3 promoted the proliferation and metastasis of gastric cancer through the modification of YAP1 mRNA m6A." (PMID 34394353, 2021). "After the knocking out of METTL3, the activity of the YAP1 signaling pathway and the proliferation and metastasis of gastric cancer were inhibited by regulating the m6A modification level of the YAP1 gene." (PMID 34394353, 2021). "On the other hand, the Hippo signaling pathway and YAP1, as its co-activator, were reported to play a significant role in the development of gastric cancer." (PMID 34768751, 2021). "In many cancers, overexpression of YAP1 is considered as a poor prognostic marker, such as gastric cancer, ovarian cancer." (PMID 32190742, 2020). "Now, our group is further investigating the regulation and functions of AGK and YAP1 gene pathways in gastric cancer development and progression." (PMID 32827244, 2020).
gastric cancer (continued). "YAP1 is a major oncoprotein that drives many different types of malignancies, including PCa, head and neck cancer, gastric cancer, colon cancer, thyroid cancer, lung cancer, ovarian cancer, and liver cancer." (PMID 33297404, 2020). "Studies showed that VP inhibits H. pyroli-induced proliferation, invasion, and metastasis of gastric cancer cells by disrupting the YAP1/TEAD4- Connective Tissue Growth Factor (CTGF) axis and blocking transcription of EMT-related genes." (PMID 33178014, 2020). "Gastric cancer development and progression are further promoted by the dysregulated YAP1/SLC35B4 axis; another mechanism involves altered IL-1β levels." (PMID 32340207, 2020). "Here, using the cDNA arrays, promoter reporter assays, and chromatin immunoprecipitation assays, we demonstrated that SLC35B4 is directly transactivated by YAP1–TEADs complex in gastric cancer (GC) cells." (PMID 31175271, 2019). "In gastric cancer (GC), YAP1/TAZ functions as an oncogene and transcriptionally promotes tumor formation by cooperating with TEAD transcription factors." (PMID 30934860, 2019). "According to this logical reasoning combined with our experiments in this study, it can help us to deeply understand the biological significance of a YAP1/SLC35B4 axis in the regulation of malignant behaviors in gastric carcinoma." (PMID 31175271, 2019). "All these results further confirmed the relationship between SLC35B4 and YAP1 in the gastric carcinoma." (PMID 31175271, 2019). "By using the promoter luciferase assay and ChIP-qPCR, we first revealed that SLC35B4 is a novel downstream gene directly regulated by YAP1/TEADs in gastric carcinoma cells." (PMID 31175271, 2019). "In the present study, we evaluated the significance of YAP1 together with HSPC111 in gastric cancer." (PMID 29113304, 2017). "Overexpression of YAP1 has been shown to correlate with disease progression and poor prognosis of gastric cancer." (PMID 27325246, 2016). "To gain insight into the role of Nodal and YAP1 in gastric cancer, we examined their expression in a panel of patient tumor samples and matched normal tissue." (PMID 27325246, 2016). "This is supported by earlier work showing that YAP1 expression correlates with progression, metastasis, and poor prognosis in patients with gastric carcinoma." (PMID 27325246, 2016). "From the target gene screening, YAP1, which was also negatively regulated by miR-375, was first identified as a novel downstream target of miR-15a and miR-16-1 in gastric cancer." (PMID 25743273, 2015). "In gastric cancer, this pathway also involves activation of the Piezo1/YAP1/CTGF axis." (PMID 41437911, 2026). "The NAT10 inhibitor Remodelin could synergize with the YAP1 inhibitor Verteporfin to fuel immune checkpoint blockade in gastric cancer." (PMID 40860183, 2025). "The overexpression of YAP1 intensifies the aggressive behavior of gastric cancer cells." (PMID 40066231, 2025). "Taken together, targeting the NAT10/XIST/YAP1 axis-mediated vascular abnormalization by using Remodelin and Verteporfin could enhance immune checkpoint blockade in gastric cancer." (PMID 40860183, 2025). "LncRNA Linc01133 promotes gastric cancer growth by increasing YAP1 nuclear location." (PMID 37929660, 2024). "In gastric cancers, expression of the Hippo pathway transcription factors YAP1 and TEAD was up-regulated in parallel with CDX2, while the negative regulators of the pathway, serine/threonine kinases MST1 and LATS1, were down-regulated, compared with normal gastric epithelia." (PMID 39768557, 2024). "In the context of gastric cancer, YAP1 is a biomarker for poor patient prognosis." (PMID 37957015, 2024). "Although loss of function of NF2 and/or gene amplifications in YAP1/TAZ have not been identified in gastric cancer, YAP1 expression is progressively elevated with advancing cancer stage when compared with expression patterns in normal gastric tissue." (PMID 37957015, 2024).
gastric cancer (continued). "Thus, YAP1 provides a novel therapeutic target across gastric cancer subtypes that arise from various oncogenic triggers in humans." (PMID 37957015, 2024). "Finally, we confirmed tumor cell–intrinsic Yap1 expression as tumor-promoting mechanism outside a Stat3-driven model (i.e., Gp130FF), also in a bona fide oncogene–driven gastric cancers model." (PMID 37957015, 2024). "Furthermore, our data provide proof-of-principle evidence that inhibition of Yap1 activity presents a targeted therapeutic opportunity to control gastric cancer." (PMID 37957015, 2024). "FGF18, a ligand for FGFR2, interacts with FGFR2, enhances F‐actin, and then promotes nuclear aggregation of YAP1; FGFR2 also activates the MAPK pathway and its downstream molecule, c‐Jun, which upregulates YAP1 transcription to promote the progression of gastric cancer." (PMID 37750089, 2023). "YAP1 is a known oncogene targeted by miR-375 in lung cancer, gastric cancer, and prostate cancer." (PMID 36894542, 2023). "LINC00662 promotes gastric cancer by targeting Hippo-YAP1 axis." (PMID 35551606, 2022). "Additionally, CLDN6 interacts with LATS1/2 to reduce LATS1/2 and YAP1 phosphorylation, influence YAP1 entry into the nucleus, and enhance the invasive ability of gastric cancer cells." (PMID 36620607, 2022). "High expressions of YAP1 and TEADs and their target genes were associated with low OS in patients with non-metastatic human gastric carcinomas." (PMID 36479120, 2022). "For example, in gastric cancer, a variety of circRNAs, such as circHIPK3, ciRS-7, and circPVT1, are upregulated to promote the occurrence and development of cancer, while circ-KIAA1244, circRNA_100269, and circ-YAP1, which play various roles in inhibiting cancer, are downregulated in gastric cancer." (PMID 33627631, 2021). "SOX9 acts as a downstream target of Yes-associated protein 1 (YAP1), which could enhance epithelial-mesenchymal transition (EMT) in gastric cancer and induce cancer stem cell properties in esophageal cancer through the Hippo-YAP pathway." (PMID 35201494, 2021). "This study analyzed whether the downstream component of the Hippo signaling pathway, YAP1, was involved in human gastric cancer to explore the mechanisms of METTL3-silencing-mediated tumor inhibition." (PMID 34394353, 2021). "In esophageal squamous cell carcinoma, YAP1 has been shown to upregulate Gli1 30, which is in accordance with our previous study in gastric cancer 30, representing that YAP1 enhances cell migration and proliferation via regulating Gli1 expression through the AKT/mTOR signaling pathway." (PMID 35003351, 2021). "Therefore, Yes-associated protein 1 (YAP1) in the Hippo pathway was selected as the target, and the relationship between METTL3 and the proliferation and metastasis of gastric cancer was proved through a series of experiments." (PMID 34394353, 2021). "In gastric cancer, YAP1 expression contributes to poor patient survival." (PMID 32827244, 2020). "To further confirm the role of YAP1 in the regulation of AGK in gastric cancer cells, we associated AGK expression with other YAP1‐related proteins in gastric cancer tissue samples and found that AGK expression was also associated with the expression of TEAD1, TEAD2 and TEAD4." (PMID 32827244, 2020). "At the molecular level, the effect of AGK might link to a suppression of the Hippo pathway and a subsequent boost of YAP1/TEADs transcription activity in gastric cancer cells." (PMID 32827244, 2020). "Circular RNA YAP1 (circYAP1) was reported to participate in progression of gastric cancer." (PMID 32160412, 2020). "In the oral squamous cell carcinoma (OSCC) and hepatocellular carcinoma (HCC), miR-526b could function as a tumor suppressor, inhibited cell growth by targeting c-Myc, and miR-526b also acts as a tumor suppressor in gastric cancer by targeting YAP1." (PMID 33344445, 2020). "This indicated that YAP1 might play important roles in the mediation of the effects of AGK in gastric cancer cells." (PMID 32827244, 2020).
gastric cancer (continued). "We also demonstrated that AGK is a novel transcription target gene of YAP1/TEADs and is able to induce YAP1/TEADs transcription activity through the inactivation of the Hippo pathway to provide a positive feedback loop of YAP1 interaction with AGK in gastric cancer cells." (PMID 32827244, 2020). "Da reported that detecting YAP1 and surviving together might help in early diagnosis of gastric carcinoma." (PMID 30539010, 2018). "Yes-associated protein 1 (YAP1) acts as an oncogene through dephosphorylation and nuclear translocation, and nuclear accumulation of YAP1 is associated with poor prognosis in gastric cancer (GC)." (PMID 29296196, 2017). "MicroRNA-506 inhibits gastric cancer proliferation and invasion by directly targeting Yap1." (PMID 26576674, 2015). "Thus, we hypothesized that XIST recruits hnRNPK to promote the nuclear translocation of the YAP1 protein and YAP1/TEAD4-mediated VEGFA transcription in gastric cancer cells." (PMID 40860183, 2025). "Interestingly, both CDX2 and HNF4α possess binding sequences in the promoter of YAP1, and a positive feed-forward loop may be operating in gastric cancers with CDX2 induction." (PMID 39768557, 2024). "Indeed, the expression of CDK4, CDK6 and cyclin D1, which are expressed predominantly in the G1 phase and promotes the transition to S phase of the cell cycle, closely correlated with the expression of YES1 and YAP1 in gastric cancer cells and tumor xenografts." (PMID 35017464, 2022). "Our findings suggest that AGK is not only a novel target of the Hippo‐YAP1/TEADs pathway but also a repressor of the Hippo pathway; thus, acting as a stimulator of the transcription activity of YAP1/TEADs to form a positive feedback circuit in gastric cancer cells." (PMID 32827244, 2020). "Supporting this, prior studies have shown co-expression of YAP1 and SALL4 in gastric cancer stem cells, suggesting a cooperative role in lineage commitment during tumorigenesis." (PMID 40932240, 2025). "STUB1 is recognized as a tumor suppressor in liver, prostate, lung, and gastric cancers through the degradation of key oncogenic proteins, such as JMJD1A, YAP1, AR1, and YTHDF2." (PMID 40859326, 2025). "Treatment of gastric cancer cells and human xenografts in mice with ursolic acid activated the kinases MST1, MST2, and LATS1 and inhibited YAP1, leading to decreased proliferation and metastases." (PMID 39768557, 2024). "We used this dataset to evaluate the expression patterns of YAP1, STAT3, IL11, IL6, TEAD1, IL6ST, and IL11RA in gastric cancer patients within the four TME subtypes." (PMID 37957015, 2024). "Surprisingly, expression of YAP1, STAT3, IL11, or IL6 mRNA transcripts remained comparable across the molecular subtypes of gastric cancer." (PMID 37957015, 2024). "PPARδ collaborates with the hippo coactivator YAP1 to elevate the expression level of SOX9 and the progression of gastric cancer." (PMID 37183261, 2023). "Previous studies have highlighted COL1A1, YAP1 and chemokine receptor CXCR4 as targets of RUNX2 that facilitate the in vitro invasion and metastatic potential of gastric cancer cells." (PMID 37256183, 2023). "RUNX2 has been shown to enhance NID1 signaling, and promote malignant progression in gastric cancer by regulating COL1A1, YAP1 and FN1 expression." (PMID 37256183, 2023). "Therefore, downregulation of YAP1 may induce apoptosis and autophagy in gastric cancer cells." (PMID 37894282, 2023). "Following the strong inactivation of YAP1 observed in LoVo cells, we decided to evaluate YAP1 localization and protein levels also in an additional MET-dependent gastric carcinoma model, GTL16." (PMID 37838732, 2023). "A recent study showed that YAP1 is a downstream effector of MAPK signaling activated by the FGFR axis, which promotes gastric cancer (GC) progression." (PMID 35883668, 2022). "We confirmed the up- and down-regulation of nucleus YAP1 by linc01133 overexpression or knockdown respectively in MKN45 and AGS gastric cancer cell lines." (PMID 35017464, 2022).